IFNAR1 (interferon alpha and beta receptor subunit 1)
Diseases named in the same sentence as IFNAR1 in open-access papers (continued):
Sharing a sentence is not in itself a finding about the gene and the disease.
viral infection (continued). "In summary, while BAFF should be involved in all forms of flaring SLE activity, the IFNAR1 could be specifically involved in flares triggered by viral infections and release of endogenous chromatin antigens." (PMID 36119023, 2022). "The effect of IFNAR1-knockout on the induction of ISGs by virus infection was then carried out." (PMID 36298780, 2022). "Because IFNAR1 undergoes ligand-dependent degradation during viral infection, this finding is consistent with the idea that sustained antiviral signaling might take place in the nervous system of ALS-FUS patients." (PMID 31875556, 2019). "Therefore, IFNAR1 signaling can differentially regulate resistance to intracellular bacterial and viral infection in humans." (PMID 29311663, 2018). "Indeed, cell cultures treated with the NS3 PI ASV after viral infection exhibited decreased HCV core antigen production which correlated with the restoration of IFNAR1 synthesis by Day 6 (62% expression relative to mock-infected cells)." (PMID 25826356, 2015). "To test whether signaling from Ifnar1 was necessary for the induction of Ch25h during viral infection, we next conducted de novo synthesis experiments in Tyk2−/− macrophage cells." (PMID 23273843, 2013). "Interestingly, unlike with STAT1 phosphorylation, we observed a comparable level of IFNAR1 between 54Stop-infected cells and uninfected cells, indicating that ORF54 is the sole viral protein responsible for IFNAR1 degradation during viral infection." (PMID 21998588, 2011). "This situation can readily be observed in deficiencies of STAT2, TYK2, IFNAR1, and IFNAR2, in which severe viral disease affects some but not all individuals, with a greater penetrance observed for infections with live-attenuated viral vaccines than for common viral infections of childhood." (PMID 41608500, 2025). "Moreover, the intracranial administration of IFNAR1-KO exhibited superior outcomes compared to intraperitoneal injection, indicating that the blood–brain barrier may modulate viral infection and replication." (PMID 40733627, 2025). "Since many rotavirus strains have been reported to inhibit Type I interferon induction to regulate a number of viral infections, we constructed IFNAR1 knockout IPEC-J2 cells to explore whether PoRVA infection promotes PEDV replication through inhibiting the IFN signaling pathway." (PMID 38905309, 2024). "Similarly, IFNAR1 KO mice were highly resistant to the Delta P80 virus infection." (PMID 39652608, 2024). "Notably, prolonged IFN signaling during chronic viral infection can promote immunosuppression through multiple cellular and molecular mechanisms, and deletion or blockade of IFNAR1 during chronic LCMV infection can alleviate immunosuppression and enhance long-term viral control." (PMID 34047696, 2021). "Mice lacking the interferon type 1 receptor (Ifnar1-/-) display enhanced susceptibility to infection by flaviviruses, and immunocompetent suckling mice are susceptible to viral infection given they have not yet fully developed a functional interferon (IFN) response." (PMID 33407600, 2021). "The preceding data suggested that despite presentation of antigen and generation of cellular immunity, a functional adaptive immune response could significantly diminish viral infection but could not fully clear it from Ifnar1-deficient innate immune cells." (PMID 27327515, 2016). "Therefore, the absence of Ifnar1 does not prevent display of antigen on cells susceptible to viral infection." (PMID 27327515, 2016). "The JAK proteins are phosphorylated upon binding of type I IFNs to IFN-α receptor 1 (IFNAR1) and IFNAR2, which then activate transcription factors such as STAT1 and STAT2 to induce transcription of ISGs that respond to viral infections." (PMID 40130878, 2025). "Type I IFNs are widely expressed by all nucleated cells following viral infection and signal through the IFN‐α/β receptor (IFNAR), which consists of subunits IFNAR1 and IFNAR2." (PMID 39931755, 2025).
viral infection (continued). "In conclusion, our present study showed that PVRL4 was elevated in host cells treated by either IFN-I or viral infections including VSV, HSV-1, IAV and SARS-CoV-2 in an IFNAR1-dependent manner." (PMID 38368366, 2024). "Moreover, efficient recognition and killing of infected cells by NK cells could compensate for Myd88 deficiency but not Ifnar1 deficiency, consistent with enhanced susceptibility to viral infections in patients harboring NK cell defects." (PMID 38777879, 2024). "Type I IFNs (IFN-α and IFN-β) are essential to mediate a wide range of innate immune responses against viral infection and share a heterodimeric receptor, IFN alpha receptor (IFNAR), comprised of IFNAR1 and IFNAR2 subunits, which is ubiquitously expressed." (PMID 38140525, 2023). "Intriguingly, blockade of type I IFN signaling using anti-IFNAR1 antibody during LCMV Cl 13 chronic infection relieved T cell suppression and led to accelerated clearance of viral infection." (PMID 37766322, 2023). "To exclude the possible role of the type III IFN-mediated antiviral response by viral infection, we knocked down STAT2 to abolish the type III IFN signaling pathway in A549-sg-IFNAR1 cells." (PMID 37327222, 2023). "Degradation of WTAP induced by viral infection reduces the m6A levels of interferon-regulatory factor 3 (IRF3) and interferon α/β receptor subunit 1 (IFNAR1) mRNAs, resulting in the suppression of IRF3 translation and destabilization of IFNAR1 mRNA." (PMID 36582239, 2022). "During viral infection, IFN-1 cytokine binding to its respective IFN receptor (IFNAR1/2) triggers STAT1 and STAT2 phosphorylation and heterodimerization." (PMID 35572196, 2022). "As the first line of antiviral defense, type I interferon (IFN) binds IFN receptor 1 (IFNAR1) and IFNAR2 to activate the Jak-STAT signal transduction pathway, producing IFN-stimulated genes (ISGs) to control viral infection." (PMID 33746965, 2021). "IFNα is critical for defense against virus infection but, unexpectedly, levels of IFNα were higher in CerS2-null liver 2 DPI compared to WT mice and downstream components of IFNAR1 signaling pathway were unaltered." (PMID 29163475, 2017). "Thus, protection of IFNAR1 from degradation in the presence of IFNs is proposed to be a new therapeutic means to enhance the efficacy of type I IFNs for the treatment of tumorigenesis, which requires higher doses of type I IFNs than those used for the treatment of viral diseases." (PMID 27356910, 2016). "Together, these results reveal an early tissue-protective effect for the blockade of IFNAR1 and highlight the role of IFN-I in driving oxidative liver damage induced by viral infections both in Sod1−/− and in WT mice." (PMID 26588782, 2015). "In duck cells, expression of IFNAR1, PIAS2 and STAT-3 was up-regulated by LPAI H2N3 or H5N1-tyEng91 virus infection." (PMID 25431115, 2014). "Since we showed the degradation of IFNAR1 in the presence of overexpressed ORF54, we assayed this phenotype during virus infection to determine the biological relevance." (PMID 21998588, 2011). "Viral infection triggered a strong upregulation of FcγRIV on inflammatory monocytes, an effect absent in type I IFN receptor-deficient (Ifnar1-deficient) mice." (PMID 41697746, 2026). "In this study, we set out to determine the detailed mechanisms of human LGP2 induction during viral infection using HeLa cells with and without IFNAR1 deletion." (PMID 41171864, 2025). "However, in Ifnar1-KO mice, pDCs become infected and produce IFN upon endogenous detection of viral infection by cytosolic sensors." (PMID 38777879, 2024). "Importantly, the pK205R7PM mutant lost its ability to interact with IFNAR1 and IFNAR2, significantly weakening the inhibitory effect on IFN-I signaling both as a single protein and during viral infection." (PMID 39405340, 2024).
viral infection (continued). "There was an elevated expression of IFNAR1 (IFNα/β receptor subunit 1), IFNAR2 (IFNα/β receptor subunit 2), IFNGR1 (IFNγ receptor subunit 1) and IFNGR2 (IFNγ receptor subunit 2) in MIS-C, bacterial infection and KD in comparison with viral infection." (PMID 39300098, 2024). "As expected, neither IFNAR1 (WT) nor IFNAR1 (W70C) in PK-15 Stat2 k/o cells showed restoration of the resistance to viral infection." (PMID 37939052, 2023). "Conversely, PK-15 Ifnar1 k/o cells reconstituted with IFNAR1 (W70C) showed no resistance to viral infection, suggesting that the restoration of antiviral activity requires reconstitution with WT IFNAR1." (PMID 37939052, 2023). "Treatment of PK-15 cells lacking Ifnar1 or Stat2 with IFNβ or poly (I:C) resulted in no inhibitory effects on viral infection by a lentiviral vector, influenza virus, and Akabane virus." (PMID 37939052, 2023). "To confirm our hypothesis, we constructed IFNAR1-deficient cell lines in both A549 cells (A549-sg-IFNAR1) and HLCZ01 cells (HLCZ01-sg-IFNAR1), as TRIM21 is able to inhibit viral infection by promoting IFN production." (PMID 37327222, 2023). "Conversely, PK-15 Ifnar1 and PK-15 Stat2 k/o cells did not resist this viral infection, suggesting that cells lacking Ifnar1 or Stat2 cannot respond to IFNβ treatment." (PMID 37939052, 2023). "Herein, we verified that α2M, but not LF, markedly upregulated IFNAR1 under viral infections or treated with rLRPAP1." (PMID 37743411, 2023). "For example, G2/I2 showed hyper-editing of type 1 interferon (IFN) receptors (IFNAR1 and IFNAR2), type 1 IFN-stimulated genes (ISGs) (e.g., EIF2AK2, DDX58/RIG-1, MAVS, TRIM56, and TRIM69) and genes involved in immune responses to viral infection (EIF2AK2, DDX58/RIG-1, MAVS, CASP8, CYCS, and HMGB1)." (PMID 35406793, 2022). "Unlike anti-BAFF, anti-IFNAR1 significantly increased the rates of certain viral infections such as HZ and perhaps influenza, a finding that connects well with its mechanism-of-action that blocks a key element of antiviral immunity." (PMID 36119023, 2022). "We previously used mouse cerebellar organotypic brain cultures (OBC) from IFNAR1 knockout (KO) (IFNAR1KO) mice to assess viral infection and spread in the absence of a type 1 interferon (IFN) response." (PMID 34061592, 2021). "While menadione treatment robustly increased virus growth in WT macrophages, it did not increase virus growth in Ifnar1-/- macrophages, suggesting that menadione interfered with the interferon response during virus infection." (PMID 32886065, 2020). "In contrast we did not detect any sign of viral infection and myelin loss in embryonic DRG obtained from immunocompetent mice but only from Ifnar1-KO mice." (PMID 29976926, 2018). "Additionally, we found that P-STAT3 inhibition did not alter susceptibility of Ifnar2−/− mice to BSI on day 3, indicating that IFNAR1 and IFNAR2 induce disparate mechanisms in response to viral infection." (PMID 30473701, 2018). "These and our previously published results imply that the presence of IFNAR2 is sufficient for controlling viral infection in Ifnar1−/− mice, but the presence of IFNAR1 in Ifnar2−/− mice is not." (PMID 30473701, 2018). "In comparison, Ifnar1−/− mice seemed to control the virus spread from the upper airways to the lungs slightly better than Ifnlr1−/− mice, indicating that IFN-λ is more potent in containing viral infections within the upper respiratory tract than type I IFN." (PMID 29651984, 2018). "To test the function of the adaptive immune system in a setting where all virally infected cells are Ifnar1-sufficient, we utilized a previously published Rag1-/- splenocyte transfer in which CD4 T cells and CD8 T cells contribute to clearance of viral infection." (PMID 27327515, 2016).
viral infection (continued). "Triggered by various stimuli, including viral infections and nucleic ligands, IFN-1 production involves PRRs and cytoplasmic sensors like cGAS, activating transcription factors such as IRFs and NF-κB, culminating in IFN-α and IFN-β production and downstream signaling via IFNAR1/2 receptors." (PMID 39061208, 2024). "Alternatively, viral infections can induce ER stress responses to protect cells from apoptosis and allow continued viral replication; activated ER stress may prevent maturation and presentation of the IFN-α receptor 1 (IFNAR1)." (PMID 37114433, 2023). "Given that key mediators of IFN-I signaling are located in the plasma membrane (e.g., IFNAR1, Tyk2), it is possible that CD24 expression alters the composition or structure of key sites within the plasma membrane, which indirectly alters steps in IFN-I responses to virus infections." (PMID 36016357, 2022). "Although virus titers were ∼5-fold higher in IFNAR1−/− mice than titers in 129 WT mice on day 5 post-infection, we found that IFNAR1−/− and IFNGR−/− mice showed no increase in susceptibility, pathogenesis or histological outcomes to rMA15 or Urbani virus infection." (PMID 20386712, 2010). "However, the knockdown of RNF149 did not affect viral infection in Ifnar1−/− MEF cells." (PMID 40245000, 2025). "While increased expression of the genes for alpha/beta or type I interferon type I (IFN-I) receptors, IFNAR1 and IFNAR2, and enhanced signaling of type I interferon pathways might be assumed to serve as protective factors due to their crucial role in controlling viral infections." (PMID 39457216, 2024). "Since some viral infections have been shown to reduce cell surface expression of IFN receptors, as a mechanism to disrupt IFN-dependent signaling, we investigated whether hMPV infection resulted in changes of IFNAR1 cell surface levels by using flow cytometry analysis of A549 and Vero cells." (PMID 21949722, 2011). "The results showed that viral infection increased the amount of mRNA of PVRL4 in A549 cells and HEK293T cells but not in the IFNAR1−/−A549 cells." (PMID 38368366, 2024). "Lack of IFN signaling also has deleterious consequences for virus infection in H7N9 infected DF1 cells, and our study demonstrated increased levels of H7N9 infection in the absence of IFNAR1 compared to WT cells." (PMID 35056582, 2022). "On the contrary, the treatment of α-IFNAR1 mAb did not affect the expression of OAS1, as the virus infection did not activate the expression of IFN-α." (PMID 35062253, 2021). "Our subsequent studies demonstrated that, even in the absence of viral infection, the activation of PRR signaling robustly induces priming phosphorylation and the degradation of IFNAR1 in a manner that requires the activation of p38 kinase." (PMID 21695243, 2011). "Additionally, upon viral infection, vimentin expression is increased, which may be influenced by IFN receptor 1 (IFNAR1), a nonspecific factor triggered by almost all viral infections, can inhibit TBK1 and IKKε during the process of enhanced vimentin expression." (PMID 37376653, 2023).
ZIKV infection (124 papers, 2016 to 2026). "We investigated the effects of dietary selenium and combined selenium plus vitamin E deficiency on ZIKV infection outcomes in a type I interferon α/β receptor knockout (Ifnar1-/-) murine model." (PMID 41754520, 2026). "Our current knowledge of the role of IFNs in protection from ZIKV infection of the FRT has been elegantly investigated largely by the use of IFNAR1 and IFNLR1 null mice that are deficient for all type-I and type-III IFN signalling, respectively." (PMID 36897927, 2023). "For example, mice which are deficient in IFNa receptor 1 (IFNAR1) are highly susceptible to ZIKV infection." (PMID 35335618, 2022). "Previous studies have shown IFNAR1-/- mice to be susceptible to clinically apparent ZIKV infection through subcutaneous route of inoculation." (PMID 34410903, 2021). "We also evaluated a cohort of pregnant IFNAR1-/- mice (n=5/group) inoculated at the same time during gestation and observed viral detection in spleen, uterus and placenta, further exemplifying the highly susceptible nature of IFNAR1-/- mice to ZIKV infection." (PMID 34410903, 2021). "Taken together, these data reaffirm the high susceptibility of IFNAR1-/- mice to ZIKV infections, allowing for infection of foetal tissues despite route of infection." (PMID 34410903, 2021). "To access the protective capacity of the formulations tested here we used a type I IFN receptor–deficient (IFNAR1–/–) mouse strain, which is susceptible to ZIKV infection." (PMID 35047887, 2020). "To carry out challenge studies, we used BALB/c mice treated with anti-Ifnar1 antibodies, which also render mice susceptible to ZIKV infection." (PMID 31717890, 2019). "This decrease in splenic Treg cells is consistent with the findings of a recent study of ZIKV infection in wildtype mice and with our earlier study in Ifnar1-deficient mice infected with DENV." (PMID 30677097, 2019). "In comparison Ifnar1-/- mice showed in general delayed disease symptoms and less body weight loss due to ZIKV infection than Stat2-/- mice." (PMID 28278235, 2017). "The difference in susceptibility to ZIKV infection between WT and Ifnar1 KO CNS cultures was marked, as anticipated from previous work." (PMID 28645311, 2017). "Thus, we treated Rag1−/− mice, which are deficient in T- and B-cells, with anti-IFNAR1 blocking antibody that inhibits signaling through the IFN-α/β receptor (subsequently called AIR mice) to reduce their resistance to ZIKV infection." (PMID 35379362, 2022). "Furthermore, to study the interplay between ZIKV and the host immune system, we adopted type-I interferon receptor-deficient (Ifnar1-/-) mice to generate a ZIKV infection model in vivo." (PMID 32150556, 2020). "Third, we examined whether CD4+ T cells could contribute to protection against ZIKV infection in fully deficient Ifnar1−/− mice, which are more susceptible than LysMCre+Ifnar1fl/fl mice to ZIKV infection." (PMID 30677097, 2019). "In our study, we observed that ZIKV infection caused elevated IOP in both IFNAR1−/− and WT mice." (PMID 31068433, 2019). "In comparison, Ifnar1-/- mice showed a delayed onset of disease, experienced less weight loss than Stat2-/- mice, displayed a wider range of neurological symptoms, and succumbed to ZIKV infection between day 7 to 8 post infection." (PMID 28278235, 2017). "Our in vivo data show that ZIKV infection actually induces PANoptosis in the placenta of Ifnar1-/- C57BL/6 dams, which lack a functional type I IFN signaling pathway." (PMID 41263557, 2025). "The role of type I interferons for placental antiviral defense is supported by the observation that pregnant Ifnar1−/− mice exhibited Zika virus infection in trophoblasts." (PMID 41288331, 2025). "Studies have demonstrated that IFNAR1 (Interferon Alpha and Beta Receptor Subunit 1) deficient mice were susceptible to DENV and ZIKV infection." (PMID 37416780, 2023).